G3BP2 (G3BP stress granule assembly factor 2)
Diseases named in the same sentence as G3BP2 in open-access papers (continued):
Sharing a sentence is not in itself a finding about the gene and the disease.
osteosarcoma (3 papers, 2022 to 2024). A usually aggressive malignant bone-forming mesenchymal neoplasm, predominantly affecting adolescents and young adults. "Then, the results of loss-of-function assays proved that knockdown of G3BP2 in osteosarcoma cells resulted in the repression of cell proliferation and invasion." (PMID 35761386, 2022). "Moreover, FGA5-AS1 was expressed evidently high in osteosarcoma cells and positively associated with G3BP2." (PMID 35761386, 2022). "For assessing the biological function of G3BP2, its expression status was first detected in osteosarcoma cell lines (Saos-2, U2OS, MG-63 and HOS) and normal cell line (HFOB1.19)." (PMID 35761386, 2022). "Accordingly, we concluded that FGA5-AS1 accelerated osteosarcoma progression by up-regulating G3BP2." (PMID 35761386, 2022). "Through the bioinformatics tools and mechanism assay, miR-124-3p was proved to target G3BP2 in osteosarcoma cells." (PMID 35761386, 2022). "Taken together, lncRNA FGA5-AS1 sponged miR-124-3p via serving as a ceRNA to adjust G3BP2 expression in osteosarcoma cells." (PMID 35761386, 2022). "Through RT-qPCR, we discovered the evidently up-regulation of G3BP2 in osteosarcoma cell lines in comparison with the normal cells." (PMID 35761386, 2022). "G3BP2 was with high expression in osteosarcoma cells, and it aggravated the malignant cell behaviors in osteosarcoma." (PMID 35761386, 2022). "In this research, our main purpose is to display the biological functions and potential regulatory mechanism of G3BP2 in osteosarcoma." (PMID 35761386, 2022). "During our investigations, we first displayed the high expression of G3BP2 in osteosarcoma cells through RT-qPCR data." (PMID 35761386, 2022). "The repressive impact of G3BP2 silencing on osteosarcoma cell proliferation was further manifested by colony formation assay." (PMID 35761386, 2022). "EBF1 induced-FGA5-AS1 aggravated osteosarcoma cell malignancy by targeting miR-124-3p and G3BP2." (PMID 35761386, 2022). "In a word, miR-124-3p negatively regulated G3BP2 osteosarcoma cells." (PMID 35761386, 2022). "In rescue assays, it was indicated that overexpressed G3BP2 could reverse the repressive effect of inhibiting FGA5-AS1 on osteosarcoma process." (PMID 35761386, 2022). "Additionally, miR-124-3p was verified to negatively regulate G3BP2 expression in osteosarcoma cells." (PMID 35761386, 2022). "Subsequently, FGA5-AS1 accelerated osteosarcoma cell proliferation through up-regulating G3BP2." (PMID 35761386, 2022). "In short, we discovered up-regulation of G3BP2 in osteosarcoma cells, and G3BP2 could accelerate cell proliferative and invasive capabilities." (PMID 35761386, 2022). "Finally, we confirmed through RT-qPCR data that enhanced miR-124-3p expression could reduce G3BP2 expression in osteosarcoma cells." (PMID 35761386, 2022). "Meanwhile, RNA pull-down assay, along with luciferase reporter and RNA immunoprecipitation (RIP) assays, was utilized to detect the interaction G3BP2, miR-124-3p and FGD5 antisense RNA 1 (FGD5-AS1) may exert on the regulation of osteosarcoma cells." (PMID 35761386, 2022). "Moreover, the interaction between G3BP2 and FGD5-AS1 and other RNAs were explored by a series of mechanism assays, which might offer a new insight for curing osteosarcoma." (PMID 35761386, 2022). "Besides, a negative correlation between G3BP2 and miR-124-3p expression was revealed in osteosarcoma cells." (PMID 35761386, 2022).
cardiac hypertrophy (2 papers, 2021 to 2023). "The role of G3BP2 in the protection of HHQ16 against myocardial hypertrophy and HF was also evaluated." (PMID 37857609, 2023). "In both in vivo animal models of lnc9456 overexpression- or LADL- induced cardiac hypertrophy and in vitro cell models of ISO- or ISO + PE- induced cardiomyocyte hypertrophy, HHQ16 consistently caused a lnc9456-depedent reduction of G3BP2 in parallel with effective inhibition of hypertrophy." (PMID 37857609, 2023).
astrocytoma (1 paper, 2022). "In a single-cell RNA-seq analysis of astrocytoma dataset, 23 out of 28 m6A-RMRs (82%) (except ALKBH5, IGF2BP1, IGF2BP2, IGF2BP3, and G3BP2) were in the medium to high expression levels in malignant cells of astrocytoma." (PMID 35211628, 2022).
COVID-19 (1 paper, 2022). A disease caused by infection with severe acute respiratory syndrome coronavirus 2. "Notably, the in situ interaction of NPSARS-CoV-2 with G3BPs was observed in the lungs of patients with COVID-19 with the S protein of SARS-CoV-2 and G3BP1 (or G3BP2) as a control." (PMID 35652658, 2022).
dementia (1 paper, 2024). Loss of intellectual abilities interfering with an individual's social and occupational functions. "PSF interacted with G3BP2 mainly in the nucleus and regulate neuron activity associated gene expressions at the RNA level, suggesting the preventive role of both RBPs for aging‐associated diseases such as dementia." (PMID 39155453, 2024). "Thus, our findings demonstrate a preventive role for the nuclear actions of gene regulation by PSF and G3BP2 in aging and dementia by sustaining neuronal cell viability." (PMID 39155453, 2024).
dengue (1 paper, 2015). "G3BP1 and G3BP2 regulate expression of ISGs known to have broad antiviral activity, and are required for an IFN response against dengue and yellow fever viruses." (PMID 26001115, 2015).
diabetic nephropathy (1 paper, 2021). "Particularly, G3BP2 was identified to aggravate the development of diabetic nephropathy." (PMID 34691148, 2021).
insulinoma (1 paper, 2025). "Our studies began by analyzing the expression of G3BP1 and its paralogue G3BP2 in glucose-responsive mouse insulinoma MIN6-K8 cells." (PMID 40355555, 2025). "We show in mouse insulinoma MIN6-K8 cells exposed to fasting glucose levels that G3BP1 and its paralog G3BP2 colocalize to cytosolic condensates with eIF3b, phospho-AMPKαThr172 and Ins1/2 mRNA." (PMID 40355555, 2025).
lymph node metastasis (1 paper, 2022). "Furthermore, high G3BP2 expression was significantly associated with lymph node metastasis (P = 0.009) and the depth of tumor invasion (P < 0.001)." (PMID 34782720, 2022).
male infertility (1 paper, 2020). The inability of the male to effect fertilization of an ovum after a specified period of unprotected intercourse. "EGFR, the signalling dysfunction of which was associated with human male infertility, might be coregulated by FXR1, FXR2, and HNRNPA1 (all of these three bind EGFR from CLIP experiments), G3BP2, G3BP1, FMR1, and SRSF7." (PMID 32316190, 2020). "CFTR, mutations of which are associated with male infertility, might be coregulated by FXR1, HNRNPA1, MATR3, PABPC1, G3BP2, FMR1, and SRSF7." (PMID 32316190, 2020).
neuroblastoma (1 paper, 2023). Neuroblastoma (NB) is the most common solid, extracranial childhood tumor. "In this study, we conducted a genome-wide investigation of the G3BP1- and G3BP2-bound RNAs using enhanced cross-linking and immunoprecipitation-sequencing (eCLIP-seq) in the human neuroblastoma (NB) cell line SH-SY5Y." (PMID 37219408, 2023).
schizophrenia (1 paper, 2024). A major psychotic disorder characterized by abnormalities in the perception or expression of reality. "The remaining genes (G3bp2, Cpne7, Atcay, Zmat4, and Nxph1) of the unique LS genes are generally understudied in their role in regulating behavior, although Zmat4 is associated with schizophrenia." (PMID 38263132, 2024).
seminoma (1 paper, 2025). A radiosensitive malignant germ cell tumor found in the testis (especially undescended), and extragonadal sites (anterior mediastinum and pineal gland). "The TGCT susceptibility genes TEX14, NARS2, and G3BP2, were identified as hub genes in both seminoma and non-seminoma networks." (PMID 39809819, 2025). "Other TGCT susceptibility genes also appeared amongst the hub genes of modules in both the seminoma and non-seminoma modules, including NARS2 in the yellow(NS) module and G3BP2 in the lightyellow(SE) module." (PMID 39809819, 2025).
superficial spreading melanoma (1 paper, 2016). A type of melanoma that typically occurs in light-skinned individuals ranging in age from young adults to the elderly. "Superficial spreading melanoma (SSM) and nodular melanoma (NM characteristically express the eight genes GALNT7, DIS3, FGFR1OP, G3BP2, MTAP, SEC23IP, USO1, and ZNF668." (PMID 27322213, 2016).
ZIKV infection (1 paper, 2023). "In addition, we used the same immune-capture approach to determine the level of m6A modification of two cellular transcripts, which were shown to be m6A methylated independent of ZIKV infection, β-actin (ACTB) and Ras GTPase-activating protein-binding protein 2 (G3BP2)." (PMID 38052817, 2023).
tumor (27 papers, 2008 to 2026). "Compared to G3BP2-R468K mutation, G3BP2-WT dramatically rescued the inhibitory effect of PRMT5 silencing on tumor growth." (PMID 36878903, 2023). "As a RNA binding protein, abnormal expression of G3BP2 exerts critical roles in gene expression homeostasis and cause tumor progression." (PMID 36878903, 2023). "On the contrary, G3BP2 expression is reduced in tumoral breast tissues; accordingly, the loss of G3BP2 enhances tumor invasion and metastasis in vivo." (PMID 35453681, 2022). "We previously reported that the stress granule‐associated protein G3BP2 is involved in the regulation of tumor‐initiating (stem) cells." (PMID 33525064, 2021). "We previously reported that the stress granule‐associated protein G3BP2 is involved in regulating tumor‐initiating (stem) cells." (PMID 33525064, 2021). "In vivo experiments showed that G3BP2 knockdown could impede increased tumor growth and tumor weight caused by EPS8L2 overexpression." (PMID 40783393, 2025). "Furthermore, hsa_circRNA_001676 deficiency notably reduced G3BP2 level, but elevated miR-556-3p level in tumor tissues from tumor-bearing mice." (PMID 37884630, 2023). "Similarly, we validated that the expression of G3BP2 was higher in HNSC than normal tissues in the TCGA-HNSC cohort, and high G3BP2 expression associated with tumor grade." (PMID 36878903, 2023). "In summary, our results reveal a novel regulatory signaling axis, PEPT1/MAP4K4/G3BP2, which is critical for inducing tumor metastasis in HCC, and provide a promising therapeutic target and prognostic indicator for patients with metastatic HCC." (PMID 38639383, 2024). "Overall, we elucidated a novel mechanism by which PEPT1‐mediated transportation of dipeptides activates MAP4K4/G3BP2 signaling to accelerate the metastasis of tumor cells." (PMID 38639383, 2024). "Considering that G3BP2 participates in tumor initiation and progression, we also investigated the role of G3BP2 in HCC metastasis." (PMID 38639383, 2024). "The authors also found that the small molecule C108—upon binding to G3BP2—reduced PD-L1 expression by enhancing mRNA degradation and promoted tumor immune cell infiltration in tumor-bearing mice." (PMID 37179344, 2023). "Our results extend the knowledge regarding of G3BP2 methylation and stabilization for tumor progression." (PMID 36878903, 2023). "Meanwhile, hsa_circRNA_001676 downregulation remarkably declined hsa_circRNA_001676 and G3BP2 levels, and elevated miR-556 level in tumor tissues." (PMID 37884630, 2023). "In this research, forced hsa_circRNA_001676 expression notably reduced miR-556-3p level, and elevated G3BP2, Oct-4 and Nanog levels in tumor tissues." (PMID 37884630, 2023). "As expected, G3BP2-WT elevated the level of triglycerides and fatty acids, but not cholesterols in Tu686 cells, supporting that methylation of G3BP2 induces lipid metabolism reprogramming in tumor cells." (PMID 36878903, 2023). "Strikingly, we observed the levels of methylated G3BP2 was correlated with tumor grade of HNSC specimens, and survival analysis suggested that elevated levels of methy-G3BP2 associated with poor overall survival." (PMID 36878903, 2023). "In this study, we revealed that G3BP2 was frequently upregulated in ESCC and was associated with lymph node metastasis, the depth of tumor invasion, and unfavorable outcomes in ESCC patients." (PMID 34782720, 2022). "To further confirm the suppressive effect of compound C108 on G3BP2 expression and tumor cell metastasis, we introduced compound C108 to KYSE30 and KYSE150 cells, which had high expression of endogenous G3BP2." (PMID 34782720, 2022). "Further analysis revealed that upregulation of G3BP2 was significantly correlated with lymph node metastasis, depth of tumor invasion and unfavorable outcomes in ESCC patients." (PMID 34782720, 2022). "Ectopic expression of HDGF effectively abolished the G3BP2 depletion-mediated inhibitory effect on tumor cell migration." (PMID 34782720, 2022).
tumor (continued). "A reduction of G3BP2 expression, tumor cell migration, and invasion were also observed in cells treated with compound C108." (PMID 34782720, 2022). "In this study, we uncover a new mechanism for MG53’s anti-tumor function involving the control of G3BP2/SG signaling." (PMID 34521423, 2021). "More in vivo studies are required to evaluate the potential combinatory effect of rhMG53 and cisplatin to determine their ability to inhibit tumor growth of drug-resistant NSCLCs, or other aggressive cancers with abnormal function of G3BP2/SG." (PMID 34521423, 2021). "High intensity G3BP2 staining was observed in the tumor region compared with non-tumor region, with distinct puncta structure in the cytosol (arrow marks)." (PMID 34521423, 2021). "Overall, these findings support the notion that MG53 functions as a tumor suppressor by targeting G3BP2/SG activity in NSCLCs." (PMID 34521423, 2021). "We also identified a significant correlation between G3BP2 and PD‐L1 co‐expression in tumor tissues from cancer patients." (PMID 33525064, 2021). "Based on these studies, inhibition of G3BP2 should have the dual effect of blocking both tumor‐initiating cells and immune checkpoint programs, thus slowing tumor progression and activating antitumor immunity." (PMID 33525064, 2021). "Consistent with findings from other investigators, we detected elevated levels of G3BP2 in tumor versus non-tumor human lung tissues." (PMID 34521423, 2021). "In concordance with the effect on cell growth, G3BP1, but also G3BP2 has been reported to be up-regulated in various tumor types and higher levels of G3BP1 have been reported in proliferating retinal epithelial cells." (PMID 24321297, 2013). "Among the genes represented in the Met library, many are associated to tumor growth, invasiveness and metastasis, such as TM4SF1, LAMA4, G3BP2, CD59 antigen, and SPP1." (PMID 18211678, 2008). "Moreover, knockdown of G3BP2 effectively suppressed EPS8L2-mediated tumor growth in vivo, suggesting that G3BP2 is a critical downstream effector of EPS8L2 in cancer progression." (PMID 40783393, 2025). "Moreover, G3BP2 was notably upregulated in HCC tissues compared to that in matched non‐tumor tissues in 10 of the 12 paired samples." (PMID 38639383, 2024). "PEPT1 is upregulated in HCC and mediated the transport of dipeptides to enhance the epithelial and mesenchymal transformation of tumor cells by inducing MAP4K4‐dependent G3BP2 phosphorylation, thereby sustaining the survival of tumor cells and facilitating HCC metastasis." (PMID 38639383, 2024). "Moreover, the staining of PEPT1, MAP4K4, and G3BP2 in tumor and non‐tumor tissues exhibited the same pattern in the lung metastasis mouse model, which was also in accordance with in vitro functional assays." (PMID 38639383, 2024). "Additionally, G3BP2 protein was also found to be participated in the processes of tumor initiation and development." (PMID 37884630, 2023). "Due to reduced G3BP2 expression, both tumor cell migration and invasion were inhibited." (PMID 34782720, 2022). "Because G3BP2 inhibition decreased PD‐L1 expression, we next investigated whether the decrease in tumor growth after genetic or C108 suppression of G3BP2 observed in our previous experiment was related to an enhanced antitumor immune response." (PMID 33525064, 2021).